IL6 (interleukin 6)
Diseases named in the same sentence as IL6 in open-access papers (continued):
Sharing a sentence is not in itself a finding about the gene and the disease.
COVID-19 (continued). "Serum levels of sCD25 correlated significantly in COVID-19 patients with age (r=0.42, p<0.01), the number of known pre-existing conditions (r=0.37, p<0.01) and the IL-6 serum levels (r=0, 29, p<0.01)." (PMID 39835136, 2024). "In WAVE I, serum levels of IL-6 significantly increased in COVID-19 patients compared to healthy controls (702.99 ± 1932.54 pg/mL vs. 1.81 ± 0.89 pg/mL, p < 0.001)." (PMID 39063569, 2024). "Evaluate the state of the cytokine balance in the tissues of the appendixes of children of selected age groups with COVID-19 based on the levels of expression of pro-inflammatory (IL-1, IL-6) and anti-inflammatory (IL-4, IL-10) markers." (PMID 38397914, 2024). "This difference is maintained, even though less significative, at T0, while at the last time point, IL-6 decreases reaching comparable levels measured in COVID-19 patients." (PMID 39582872, 2024). "In COVID-19 patients hospitalized with symptoms, the unregulated production of IL-6 has been shown to correlate with the illness severity and progression and predict respiratory failure." (PMID 38390960, 2024). "We conducted an analysis to explore the potential impact of IL-6 polymorphisms, specifically rs1800795 and rs1800797, on complete blood count (CBC) and D-dimer levels in COVID-19 patients." (PMID 38783290, 2024). "IL-6 has been demonstrated to play a leading role in cytokine storm syndrome and, as for COVID-19, the severity of the disease positively correlates with enhanced IL-6 and C-reactive protein serum levels." (PMID 38542436, 2024). "Excessive IL-6 levels, acting as an axis for cytokine storms in COVID-19 patients, correlate with severe diseases." (PMID 38707035, 2024). "Despite the limitations, the present study was able to shed some light on the association of cytokines, especially IL-6, IL-10, and IFN-γ, with COVID-19 disease severity." (PMID 38707035, 2024). "In contrast, IL-8, D-dimer, IL-6, Angpt-2, Tie-2, uPAR, and SP-D were higher in females with critical-COVID-19 than in severe cases." (PMID 39507250, 2024). "Tocilizumab, an IL-6 pathway inhibitor, has shown reduced duration of ventilator dependency and mortality in critically ill patients with COVID-19." (PMID 38778074, 2024). "In this scenario, IL-6 acts on the endothelial cells of the pulmonary capillaries, leading in the most severe cases of COVID-19, to an excessive and uncontrolled immune response." (PMID 39281667, 2024). "The gene expression of the core pro-inflammatory cytokines in COVID-19, IL-6, and TNFα, were significantly lower with OmeGo than in the BSC group (p < 0.01)." (PMID 39000027, 2024). "We report that the levels of ferritin, hepcidin, zinc, CRP, and IL-6 are higher in patients with COVID-19 in the ICU in the intergroup comparison in both the higher altitude region and the lower altitude region." (PMID 39062181, 2024). "We found increased levels of respiratory IL-6 and IL-10 in patients with more severe COVID-19 compared to less severe patients." (PMID 39633683, 2024). "We calculated the sensitivity and specificity of CRP and IL6, using the established laboratory reference ranges or cut-off values, to predict hospitalization and severe COVID-19, respectively, in our study cohort." (PMID 39664394, 2024). "In our study, we observed elevated serum levels of hs-CRP, PCT and IL-6 in both mild and severe COVID-19 cases, with significantly higher levels in severe cases than in mild ones." (PMID 38576608, 2024). "Previous studies have reported the usefulness of the partial pressure of arterial oxygen (PaO2)/fraction of inspiratory oxygen (FiO2) ratio, the SpO2/FiO2 ratio, alveolar–arterial gradient, and IL-6 as parameters for predicting severity in COVID-19 patients." (PMID 39125944, 2024). "TLR or/and C5aR-mediated induction of IL-6 production and secretion by macrophages can lead to a shift in the balance in the differentiation of naive T cells towards Th-17 in COVID-19 patients." (PMID 39457048, 2024).
COVID-19 (continued). "Clinically, IL-6 inhibition promotes anti-inflammatory effects, and inhibitors are used in various disorders including RA, COVID-19 and cytokine release syndrome." (PMID 38840141, 2024). "In severe COVID-19, the cytokine storm results from a hyperactive Th1/Th17 immune response, leading to elevated IL-6 and TNF-α." (PMID 40735669, 2024). "Tocilizumab is a monoclonal antibody of IL-6 membrane and soluble receptors used as treatment of some rheumatoid diseases and approved for the treatment of COVID-19 patients." (PMID 38687065, 2024). "Previous trials have demonstrated a close link between COVID-19 disease severity and elevated IL-6 levels; however, most IL-6 neutralizing agents, such as tocilizumab, have shown modest benefit in patients hospitalized with COVID-19." (PMID 36445625, 2024). "Potential associations within COVID-19 group between heteroplasmic variant burden, along with the averaged REA values, and inflammatory mediators such as IL-6, IFN-α, TNF-α, and IL-10 were analyzed by Spearman rank correlation analysis." (PMID 38377022, 2024). "Shifting focus to COVID-19, the cytokine storm observed in this disease is triggered by the release of interleukin-6 (IL-6) from alveolar macrophages." (PMID 38932276, 2024). "interleukin-6 (IL-6), IL-10, tumor necrosis factor (TNF)-α, IL-1β, IL-4, IL-8 and IL-17 are associated with increased severity as well as mortality in COVID-19 patients." (PMID 38544825, 2024). "Further, it has been confirmed that increased levels of IL-6 and IL-10 are independent and significant predictors of the severity and mortality of COVID-19." (PMID 38355623, 2024). "To facilitate visualization, we developed a nomogram for predicting serum IgG levels using age, IL-6 levels, COVID-19 vaccine doses, and comorbidities." (PMID 39717543, 2024). "NMR, NLR, CRP, IL6, PCT, and DD were identified as relevant factors associated with the risk of COVID-19-related death." (PMID 39555074, 2024). "Treatment of bone marrow-derived macrophages with COVID-19 EVs enhanced the M1 phenotype and augmented the production of IL-1β, IL-6, and TNF-α." (PMID 39475319, 2024). "Investigations show that the levels of tumor necrosis alpha (TNFα) and Interleukin (IL-6) are high in patients with COVID-19 And in severe cases of COVID-19, the production of IL-6 and TNF-α and other cytokines is profoundly increased." (PMID 39118801, 2024). "Elevated expression of IL-6 has been correlated to a poor prognosis for COVID-19 patients in several studies." (PMID 40603504, 2024). "In summary, our study underscores the predictive value of the Neutrophil-to-Lymphocyte Ratio (NLR) and cytokine profiles, particularly IL-6 and IL-10, as markers in COVID-19." (PMID 39203987, 2024). "In chronic COVID-19, elevated levels of both IL-6 and adenosine have been observed, with IL-6 contributing to the proinflammatory ‘cytokine storm’ and adenosine being considered as a potential therapeutic for severe cases due to its anti-inflammatory effects." (PMID 38527092, 2024). "CSF proinflammatory cytokines, including IL-6, had been found markedly increased in adults with COVID-19 and neurological symptoms." (PMID 39744636, 2024). "To assess the consequences of NLRP3-inflammasome and caspase-1 activation in COVID-19 patients, we measured the levels of IL-1β, IL-1Ra and IL-6 in both BALF and serum of C-ARDS or NC-ARDS patients and in control subjects." (PMID 39882243, 2024). "The study excludes conditions such as diabetic ketoacidosis, patients with end-stage renal disease, and conditions that increase IL-6, such as COVID-19." (PMID 39280507, 2024). "Our study aimed to measure NEAT-1, miR-374b-5p, and IL6 in the serum of COVID-19 patients, demonstrating a correlation between target genes to explore the possible relationship between them." (PMID 39729489, 2024).
COVID-19 (continued). "In the context of severe viral infections like COVID-19, pathways involving inflammatory cytokines and chemokines, such as IL-6, IL-1β, and TNF-α, are significantly elevated, contributing to cytokine release syndrome (CRS)." (PMID 39458339, 2024). "In COVID-19 hyperinflammation condition, high levels of IL-6 seem to be the main prognostic factor for poorer outcomes." (PMID 38632501, 2024). "Our findings also suggested an elevation in IL-6 levels in T2DM-affected COVID-19 subjects, which further showed a strong and positive correlation with serum PAR-1 levels." (PMID 38675414, 2024). "In COVID-19 patients, a decrease in IL6 mRNA expression indicates a reduction in inflammatory reactions and gradual recovery." (PMID 38543303, 2024). "At <6 DPOS, a model with FLT3, IL-17, IL-6, IL-15 emerged as the minimal cytokine set that explained 62% of variability in COVID-19 hospitalization (Akaike information criterion or AIC = 41.4; n = 49)." (PMID 39650666, 2024). "Nevertheless, the literature data have indicated that proinflammatory cytokines, such as IL-6, play a pivotal role in the development of acute lung injury in COVID-19." (PMID 38391578, 2024). "As a use case for COVID-19, the present study inferred that IL-6 and IL-8 are inflammatory substances in COVID-19 and are SASP factors in cellular senescence." (PMID 38729991, 2024). "The infusion of intravenous hydrocortisone in patients with severe COVID-19 reduces the amount of interleukin 6 in the lungs, thus reducing the inflammation that occurs in the acute respiratory syndrome related to COVID-19." (PMID 39202769, 2024). "IL-6 is a specific arbitrator of inflammation and cytokine storm induced virally in COVID-19 patients." (PMID 37742314, 2024). "Among the cytokines examined, IL-6 stood out, showing the most pronounced variations across COVID-19 severity groups, with a discernible trend when comparing patients with cancer and COVID-19 to both CC and HV." (PMID 39272832, 2024). "While arachidonic acid appears useful in distinguishing COVID-19, IL-6 emerges as a superior marker for diagnosing this and other infectious diseases." (PMID 39066228, 2024). "The main inflammatory cytokines and chemokines widely produced by patients with severe forms of COVID-19 are IL-6, IL-8, IL-1β, TNF-alpha, IFN-gamma, MIP1α and 1β, CCL2, CCL5, CCL20, CXCL1, CXCL2, CXCL8, CXCL10, and CXCL17." (PMID 39768136, 2024). "The other two recommendations evaluated the use of interleukin-6 blockers and the use of baricitinib in individuals with severe and critical COVID-19." (PMID 39318885, 2024). "A study has found that inflammatory factors including IL-2, YKL40, IL-4, IL-6, IL-10, sCD40L, TNF-α, IL-1Ra, interferon-gamma (IFN-γ), and CRP, are associated with cognitive impairment in COVID-19 patients." (PMID 38012459, 2024). "Inflammatory cytokines, such as IL-6 have been used as biomarkers of disease severity in COVID-19, and in this PVM model peaked at 8 dpi in BAL fluid." (PMID 39439800, 2024). "In fact, exacerbated activation of NF-kB has been reported in patients with severe COVID-19 and high levels of IL-6, which highlights the importance of the pathway in the clinical course of the disease." (PMID 39637135, 2024). "The results demonstrated that age, IL-6 levels, COVID-19 vaccine doses, and comorbidities independently predicted serum IgG levels ≥ 21.08 g/L (P < 0.05)." (PMID 39717543, 2024). "IL-6, as a biomarker for the prognosis and treatment response of COVID-19 patients, has been extensively studied and applied in clinical practice; however, the measurement of individual cytokine levels alone cannot fully reflect the immune status of patients." (PMID 39654886, 2024). "In patients with COVID-19 complicated by acute respiratory distress syndrome, hyperactivation of the immune system with prominent IL-6 response can lead to organ dysfunction." (PMID 38394183, 2024).
COVID-19 (continued). "Considering these findings, the coexistence of elevated NLR and cytokine levels, particularly IL-6 and IL-10, offers a window into the complex dynamics of the immune response to COVID-19." (PMID 39203987, 2024). "This contrasts with findings from other studies, where severe COVID-19 cases showed a higher IL-6/IFN-γ ratio than milder cases, suggesting a stronger cytokine storm leading to lung damage." (PMID 39061002, 2024). "IL-6 is one the major inflammatory molecules present in the cytokine storm response in COVID-19 patients, and we have demonstrated that HBMEC exposed to SARS-CoV-2 also display increased IL-6 expression." (PMID 38532784, 2024). "MO secreting IL-6 has also been detected in the peripheral blood of patients with COVID-19 in intensive care units." (PMID 38915037, 2024). "In accordance with our results, previous studies demonstrated that COVID-19 is associated with elevated levels of TNF, IL-1β, and IL-6." (PMID 38187222, 2024). "Previous research has identified cytokine profiles, particularly elevated Il-6, as indicators of disease severity and poor prognosis in COVID-19 patients." (PMID 38935767, 2024). "The concentration of plasma IL-6 in COVID-19 patients with myocardial injury was increased, and there were many abnormal cytokines in COVID-19 patients." (PMID 38898389, 2024). "Decrease in calprotectin and C-reactive protein levels, IL-6 in hospitalized patients supplemented with probiotics corroborated their beneficial role in COVID-19." (PMID 38178223, 2024). "In patients with severe COVID-19, a cytokine storm is often triggered, characterized by an excessive release of pro-inflammatory cytokines such as IL-6, TNF-α, and IL-1β." (PMID 39720706, 2024). "In this account, studies show that in patients with COVID-19, the level of tumor necrosis alpha (TNFα) and interleukin-6 (IL-6) is high and in severe cases of COVID-19, the production of IL-6, TNF-α, and other cytokines increases profoundly." (PMID 39118801, 2024). "Among these, interleukin 6 (IL-6) antagonists, including tocilizumab and sarilumab, have been suggested for the treatment of patients with severe COVID-19." (PMID 39062668, 2024). "Serum levels of the pro-inflammatory cytokine IL-6 were measured in all patients to assess the COVID-19-related peripheral immune-inflammatory milieu." (PMID 38731010, 2024). "Ferritin, interleukin-6, or d-dimer provide insight into the immunological and inflammatory pathways involved in severe COVID-19." (PMID 39768627, 2024). "Conversely, species such as Bacteroides dorei and Akkermansia muciniphila, which were enriched in the COVID-19 cohort, positively correlated with proinflammatory cytokines IL-1β, IL-6, and CXCL8, potentially exacerbating inflammation." (PMID 39518964, 2024). "A phase 2 open-label interventional trial showed that aerosol inhalation of exosomes derived from human adipose-derived mesenchymal stromal cells decreased IL-6 levels in patients with severe COVID-19." (PMID 38612615, 2024). "Current treatment strategies are increasingly focused on inhibiting IL-6 trans-signaling, which offers promise for more precise therapeutic approaches to manage hyperinflammatory responses in COVID-19." (PMID 39518964, 2024). "The number of patients given IL-6 antagonist therapy (tocilizumab) to treat COVID-19 was too small (n = 4) to allow a statistical analysis of this factor." (PMID 38285382, 2024). "A number of cytokines signal through the JAK-STAT pathway, including IL-6, IL-2, IL-15, and IL-10, which are elevated in patients with COVID-19." (PMID 39599762, 2024). "It has also been reported that the constitutive activation of NF-κB and enhanced TNFα, IL-1β, and IL-6 levels is a ubiquitous phenomenon among various cell types in severe COVID-19 patients." (PMID 37872376, 2024).
COVID-19 (continued). "Characteristic features of severe infection with COVID-19 include a hyper-inflammatory condition that involves augmented levels of inflammation markers, such as IL-6 and CRP, and increased levels of ferritin." (PMID 39301327, 2024). "In COVID-19, IL-6 is frequently described as a pro-inflammatory cytokine that plays an important role in pathogen resistance and tissue homeostasis." (PMID 39729489, 2024). "In COVID-19, the immune system overreacts, leading to the release of large quantities of pro-inflammatory cytokines such as interleukin-6, tumour necrosis factor-alpha, and interferon-gamma." (PMID 38241342, 2024). "IL-6 concentrations were higher in both COVID-19 patient groups compared to the respective control cohorts." (PMID 39597537, 2024). "Interleukin-6 (IL-6), an important proinflammatory cytokine, has been proven to play an important role in the neurological manifestation of COVID-19." (PMID 39274228, 2024). "In 219 COVID-19 patients, a previously identified proteomic glycocalyx signature correlated with IL-6 (p < 0.0001)." (PMID 39685503, 2024). "In a similar vein, a retrospective observational study involving hospitalized COVID-19 patients revealed that if the serum level of IL-6 exceeded 30 pg/mL, it was a predictor of the need for invasive mechanical ventilation." (PMID 38459174, 2024). "Evidence of how high levels of interleukin-6 (IL-6) stimulate megakaryocytopoiesis in the bone marrow and abnormal lung immunothrombosis in severe COVID-19 patients has been proven in postmortem and biopsy examinations." (PMID 38543815, 2024). "Grifoni, E. and others have shown that IL-6 is detected in high levels in the blood of patients with COVID-19." (PMID 38397914, 2024). "The level of IL-6 was found to be much greater in COVID-19 patients and correlated with disease severity." (PMID 38982355, 2024). "Their research findings shed light on the notable impact of Imatinib on modulating inflammatory markers, such as IL-6, within the patient population afflicted with COVID-19." (PMID 38522056, 2024). "A significantly increased ALT level as well as higher inflammatory indices (CRP, LDH, ferritin, and procalcitonin) and IL-6 levels were detected in COVID-19 patients compared to controls, with the highest values in severe and critically ill patients." (PMID 38703289, 2024). "There are reports of elevated serum levels of these cytokines (TNF-α, IFN-γ, IL-2, IL-4, IL-6, and IL-10) in patients with COVID-19." (PMID 39062181, 2024). "CRP and IL6 were the biomarkers with the highest discriminatory capacity for hospitalization, and severe COVID-19, respectively." (PMID 39664394, 2024). "Our study provides valuable insights into the role of IL-6 in severe COVID-19 cases across different phases of the pandemic." (PMID 39063569, 2024). "TCZ was found to be safely administered also in the occurrence of a SARS-Cov-2 infection according to previous reports indicating how both in MOGAD and during COVID-19 there is an increase in pro-inflammatory cytokines including IL-6." (PMID 38010585, 2024). "In this study, we selected from our cohort of patients who had been hospitalized for COVID-19, those patients meeting requirements for anti-Il-6 treatment." (PMID 38248262, 2024). "Previous reports have found that the median levels of CRP and IL-6 in patients infected with COVID-19 are 5.56 mg/L and 9.52 pg/mL, respectively." (PMID 39628680, 2024). "Another study reported that COVID-19 severity was related to decreased vitamin D levels, which were in turn associated with increased ACE2 and IL-6 levels." (PMID 39339670, 2024). "Regarding RAASI, only plasma IL-6 (22 vs. 44 pg/mL, p = 0.012) levels were found to be significantly lower in COVID-19 patients with CVD consuming these medications compared to patients who did not have any CVD." (PMID 39518552, 2024).